CNNM2 (cyclin and CBS domain divalent metal cation transport mediator 2)
Diseases named in the same sentence as CNNM2 in open-access papers (continued):
Sharing a sentence is not in itself a finding about the gene and the disease.
Seizure (5 papers, 2014 to 2024). A seizure is an intermittent abnormality of nervous system physiology characterized by a transient occurrence of signs and/or symptoms due to abnormal excessive or synchronous neuronal activity in the brain. "Patients with recessive CNNM2 mutations exhibit structural brain deformities, such as demyelination, failure of opercularisation, and cerebral cortical atrophy, often concomitant with motor skill defects, epileptic seizures, and intellectual disability." (PMID 33859252, 2021).
epilepsy (4 papers, 2021 to 2023). A brain disorder characterized by episodes of abnormally increased neuronal discharge resulting in transient episodes of sensory or motor neurological dysfunction, or psychic dysfunction. "In summary, we reported two cases first in the Chinese population with hypomagnesemia, epilepsy, and DD caused by novel de novo heterozygous variants in CNNM2 (c.814T>C [p.Phe272Leu] and c.976G>C [p.Val326Leu])." (PMID 34604137, 2021). "We summarized and clarified phenotypes of CNNM2-related disorders into three types: AD-inherited simple hypomagnesemia; AD-inherited hypomagnesemia with epilepsy and ID/DD; and AR-inherited hypomagnesemia with epilepsy and ID/DD." (PMID 34604137, 2021). "The effects of AS3MT on epilepsy might involve multiple targets including CNNM2, CACNB2, TRIM26, MTHFR, GSTM1, CYP17A1, NT5C2, and YBX3." (PMID 34899152, 2021). "We found that the previously established pleiotropy between genetic risk for IA and the genes targeted by anti-epileptic drugs is not driven directly by an increased predisposition for epilepsy also affecting IA risk but is partly explained by variation in gene expression of CNNM2." (PMID 36300369, 2023). "Bioinformatics analysis revealed that the effects of AS3MT on epilepsy likely involved multiple targets including MTHFR, GSTM1, CYP17A1, NT5C2, YBX3, CNNM2, CACNB2, and TRIM26." (PMID 34899152, 2021).
brain malformations (3 papers, 2014 to 2024). "CNNM2 function is in line with its expression in the DCT and brain, as heterozygous knockout (Cnnm2+/−) mice develop hypomagnesaemia due to decreased Mg2+ reabsorption, while a full knockout (Cnnm2−/−) is perinatally lethal and leads to brain malformations in a subgroup of mice." (PMID 38519529, 2024).
coronary artery disease (3 papers, 2014 to 2025). "A genetic variant in CNNM2, encoding for a cyclin and CBS domain divalent metal cation transport mediator 2, has been associated with coronary artery disease and blood pressure." (PMID 31167428, 2019).
Obesity (3 papers, 2022 to 2024). Accumulation of substantial excess body fat. "Additional features of CNNM2-related disorders seen in subgroups of affected individuals include obesity and motor skill defects." (PMID 38519529, 2024). "The impact of NT5C2 rs11191580 polymorphism on infants' obesity may function through the region of linkage disequilibrium of several genes (NT5C2, CYP17A1, and CNNM2)." (PMID 35295960, 2022). "The most striking finding is the absence of seizures, ID, and obesity in the majority of the cases described here, suggesting that variants may independently affect renal and extrarenal functions of CNNM2." (PMID 38519529, 2024).
breast carcinoma (2 papers, 2016 to 2025). "In addition, CNNM2 activity was suggested previously to regulate the TRPM7 magnesium channel that is associated with breast cancer growth and metastasis, which may also provide a third model of magnesium regulation in cancer by the PRL-CNNM complex." (PMID 26969161, 2016).
cardiac arrhythmia (2 papers, 2016). Any disturbances of the normal rhythmic beating of the heart or MYOCARDIAL CONTRACTION. "A rare genetic disease (MIM:607803) conferring hypomagnesaemia, i.e., low Mg2+ level in the blood leading to tetany, seizure and cardiac arrhythmia, has been mapped to mutations in CNNM2, which is involved in Mg2+ excretion in kidney." (PMID 27933050, 2016).
colorectal cancer (2 papers, 2023 to 2025). A primary or metastatic malignant neoplasm that affects the colon or rectum. "In our study CNNM2 was also significantly low expressed in colorectal cancer, which is consistent with our findings." (PMID 41174507, 2025). "In the “Other tumors group” four rearrangements involving BRAF gene were detected (three melanoma: BRAF::CNNM2, BRAF::ERC1, BRAF::MAD1L1 and one pancreatic adenocarcinoma BRAF::SND1), but also one ETV6::NTRK3 (colorectal cancer) and one FGFR3::TACC3 (urothelial cancer)." (PMID 37708140, 2023).
Anxiety (1 paper, 2023). Intense feelings of nervousness, tension, or panic often arise in response to interpersonal stresses. "Of the 11 gene scores in the anxiety symptom group, we replicated six genes, including CNNM2, EXD3, GBF1, NT5C2, NOLC1 and TRIM." (PMID 37322117, 2023).
autoimmune disease (1 paper, 2025). A disorder resulting from loss of function or tissue destruction of an organ or multiple organs, arising from humoral or cellular immune responses of the individual to their own tissue constituents. "We identified 12 pleiotropic genes, including PLCL1, SPRED1, and CNNM2, associated with the comorbidity of DeP and autoimmune diseases." (PMID 41212883, 2025).
Bartter syndrome (1 paper, 2020). "Furthermore, we identified variants of uncertain significance in the CNNM2 gene in two patients previously diagnosed of Bartter syndrome." (PMID 32997713, 2020).
development (1 paper, 2025). "Mutations in CNNM2 are associated with hypomagnesemia, seizures, and impaired intellectual development." (PMID 40790246, 2025).
Epileptic encephalopathy (1 paper, 2020). A condition in which epileptiform abnormalities are believed to contribute to the progressive disturbance in cerebral function. "It has been described that homozygous mutations in the CNNM2 gene cause hypomagnesemia, epileptic encephalopathy, brain malformations and mental retardation." (PMID 32997713, 2020).
hypercalcaemia (1 paper, 2024). "Moreover, two cases described here and the Cnnm2+/− mice have hypercalcaemia rather than hypocalcaemia, further complicating the interpretation of this association." (PMID 38519529, 2024).
Hypercholesterolemia (1 paper, 2016). An increased concentration of cholesterol in the blood. "The same approach applied to hypercholesterolemia identified three genes also associated with MI: MIA3, CNNM2, and TRIB1; suggesting their role in MI could be mediated through lipid metabolism." (PMID 27640124, 2016). "Three individual genes (MIA3, CNNM2, and TRIB1) and 44 gene pairs overlap between MI and hypercholesterolemia." (PMID 27640124, 2016).
hyperparathyroidism (1 paper, 2024). Hyperfunction of the parathyroid glands resulting in the overproduction of parathyroid hormone. "Although it is unclear whether the sporadic observations of hyperparathyroidism and Ca2+ disturbances are directly linked to CNNM2 function, these findings indicate that CNNM2 variants should be considered earlier in individuals with unsolved Ca2+ and PTH phenotypes." (PMID 38519529, 2024).
hypocalcaemia (1 paper, 2024). "However, these individuals typically have lower serum Mg2+ levels than observed in individuals with CNNM2 variants and the prevalence of hypocalcaemia is too rare to conclude it is directly related." (PMID 38519529, 2024).
magnesium deficiency (1 paper, 2022). A nutritional condition produced by a deficiency of magnesium in the diet, characterized by anorexia, nausea, vomiting, lethargy, and weakness. "Among the classification variables, age group, city-type, and CNNM2 rs3740393 gene subgroup were all protective factors of magnesium deficiency." (PMID 35215497, 2022).
nephrolithiasis (1 paper, 2024). The presence of a calculus in the pelvis of the kidney; this is most often composed of mineral salts and proteins. "A variant in CNNM2 (c.1291G>A, p.E431K) was found in both after analyzing WES data using hypomagnesaemia and nephrolithiasis gene panels." (PMID 38519529, 2024).
osteosarcoma (1 paper, 2023). A usually aggressive malignant bone-forming mesenchymal neoplasm, predominantly affecting adolescents and young adults. "Furthermore, a disease‐free survival (DFS) predictor model of osteosarcoma, including ZNF720, REEP3, CNNM2, and CGREF1, can be created using TARGET datasets, demonstrating that a combination of multiple genes may be responsible for cisplatin resistance." (PMID 36408691, 2023).
ovarian carcinoma (1 paper, 2023). A malignant neoplasm originating from the surface ovarian epithelium. "Interestingly, none of the four top genes WBP1L, ASAP3, CNNM2, and NCAPH2 was correlated with ovarian cancer pathogenesis previously." (PMID 36856946, 2023).
renal hypomagnesemia-6 (1 paper, 2025). "In 2011, first proposed that heterozygous CNNM2 gene mutations were associated with renal hypomagnesemia-6 (HOMG6, OMIM #613882)." (PMID 40612795, 2025).
cancer (3 papers, 2016 to 2025). A tumor composed of atypical neoplastic, often pleomorphic cells that invade other tissues. "The findings that ANK3 and CNNM2 are low expressed in various cancers and associated with better survival outcomes suggest that these genes may serve as useful prognostic biomarkers." (PMID 41174507, 2025). "The mutation rates of different MHGs varied widely across cancer tissues, with ANK3 having the highest mutation rate (47%), followed by KEL (18%), TRPM7 (16%), KCNA1 (13%), CNNM2 (9%), CNNM1 (9%), TFAP2B (9%), CNNM4 (9%), XK (7%), and EDN3 (5%)." (PMID 41174507, 2025). "The downregulation of their expression is associated with better prognosis in several cancers, such as XK in ACC, CNNM4 in READ, KEL in CESC, CNNM3 in KIRC, as well as CNNM2 in LGG and KIRC." (PMID 41174507, 2025). "CNNM2 is thought to promote cell replication and enhance migration and invasion of cancer cells through the formation of PRL-CNNM complexes." (PMID 41174507, 2025). "mRNA expression of MHG was positively correlated with CNV in most cancers, such as SLC41A1, CNNM2, and TRPM7 in SKCM, LUAD, SARC, BRCA, LUSC and OV (P < 0.05)." (PMID 41174507, 2025). "EDN3, TFAB2B showed high levels of methylation in almost all cancers, while CNNM1, CNNM2 and KCNA1 showed high levels of methylation in at least half (7 or more) of the cancers." (PMID 41174507, 2025). "In previous reports, CNNM2, one member of the CNNM family, which contains four integral membrane proteins (CNNM1‐4), played a unique role in maintaining intracellular Mg2+ homeostasis and for its biological functions related to various cancers." (PMID 36408691, 2023).
calcium metabolism disorder (1 paper, 2020). "Thus, a novel likely pathogenic variant in the CNNM2 gene (p.(Ser795*)) has been found associated to dominant hypomagnesemia in a patient previously suspected of a calcium metabolism disorder." (PMID 32997713, 2020).
neurodevelopmental disorder (1 paper, 2025). A behavioral and cognitive disorder with onset during the developmental period that involves impaired or aberrant development of intellectual, motor, or social functions. "Future studies could reveal further pathogenic mechanisms through which CNNM2 contributes to neurodevelopmental disorders by utilizing additional cell models, such as SH-SY5Y cells or iPSC-derived neurons." (PMID 40612795, 2025).
neurological disorders (1 paper, 2024). "HOMGSMR1 and HOMG6 are caused by mutations in CNNM2 and are characterized by low plasma magnesium and abnormally high renal excretion of magnesium associated with neurological disorders." (PMID 39614204, 2024).
tumor (1 paper, 2025). "Targeting Mg2+ transporters—such as CNNM2 inhibitors or TRPM7 activators—may simultaneously block tumor Mg2+ uptake and amplify T cell functionality." (PMID 41174507, 2025).
CNNM2 also shares sentences with these, for which no sentence is quoted: myocardial infarction (3 papers); melanoma (2); Type 2 diabetes (2); abdominal aortic aneurysm (1); alcoholism (1); amelogenesis imperfecta (1); aneurysm (1); autism (1); Bartter syndrome type 3 (1); Bartter syndrome type 4 (1); cardiovascular disorder (1); Cerebral cortical atrophy (1); depression (1); developmental delay (1); EAST syndrome (1); Gitelman syndrome (1); Hypocalciuria (1); Infertility (1); insomnia (1); intracranial aneurysm (1); Jalili syndrome (1); metabolic syndrome (1); pancreatic adenocarcinoma (1); psychiatric disorder (1); pulmonary hypertension (1); retinal cone-rod dystrophy (1); Sleep apnea (1); Stroke (1); thoracic aortic aneurysm (1).